KRAS (KRas proto-oncogene, GTPase)
Diseases named in the same sentence as KRAS in open-access papers (continued):
Sharing a sentence is not in itself a finding about the gene and the disease.
tumor (continued). "We sequenced KRAS and BRAF, assessed CpG island methylator phenotype (CIMP) frequency, and analyzed DNA mismatch repair enzyme levels using immunohistochemistry in tumor samples." (PMID 28422723, 2017). "Collectively, these data demonstrate that combined MEK and ERK inhibition is functionally unique, yielding greater than additive anti-tumor effects and elucidates a highly effective combination strategy in MAPK-dependent cancer, such as KRAS mutant tumors." (PMID 28982154, 2017). "Many tumor-promoting proteins, including KRAS, EGFR, SRC family kinases, and integrins are specifically enriched in exosomes from mutant KRAS cells." (PMID 29246022, 2017). "To delineate the contributions of serum versus autocrine secretion of RBP4 in the tumor microenvironment, we measured serum levels of RBP4 in a subset of patients from the KRAS wild-type and mutant groups." (PMID 28689994, 2017). "Analysis of data from the phase III PRIME study of panitumumab + FOLFOX4 confirmed the importance of RAS testing beyond KRAS in patients with mCRC and was possible due to the availability of RAS data for 90% of the KRAS WT tumour samples." (PMID 28424871, 2017). "Many genes in these chromosome lesions, such as EGFR (amp 7p11.2), MET (amp 7q31.2), KRAS (amp 12p12.1), and CACNA2D2 (del 3p21.31), are known to be related to tumor invasion and metastasis." (PMID 28922552, 2017). "Prediction of potential targets for the identified miRNAs indicates the overexpression of KRAS, BCL2 and down-regulation of PTEN in PCa tumor tissues." (PMID 29268752, 2017). "In our study there was tumor overexpression of EGFR (2 times more) and KRAS (5 times more) compared to tumor-free lungs." (PMID 29285236, 2017). "For example, the combination of trametinib and CDK4/6 (cyclin dependent kinase 4/6) inhibitor was shown to be highly efficacious in inhibiting the growth of KRAS-mutant CRC cells and inducing the tumor regression in patient-derived xenograft models of CRC." (PMID 28756770, 2017). "While PEAK1 is upregulated in both genetic backgrounds within PDAC cells under physiologically relevant tumor microenvironment conditions (i.e., the orthotopic site in nude mice), MST1R is only upregulated in KRas mutant cells implanted at this site." (PMID 27602776, 2017). "The result of these mutations is constitutive activation of the KRAS signaling pathway and it has been shown that if activation of KRAS and WNT signaling are combined, the joint activation leads to increased tumor size." (PMID 28870231, 2017). "The dependency of KRAS mutant tumor cell lines upon CDK6 was readily apparent (rho = −0.38), but was stronger when KRAS, HRAS, NRAS, or BRAF mutant tumor cell line models were combined as a group (rho = −0.43)." (PMID 26947069, 2016). "We also provided evidence that the restoration of KRAS expression could partly rescue miR-16-suppressed cell proliferation and invasion and miR-16-induced apoptosis, suggesting that the targeting of KRAS is an important mechanism by which miR-16 exerts its tumor-suppressive function." (PMID 27857191, 2016). "(under sub-section B), Corcoran and colleagues used a synthetic lethal screen in KRAS mutant tumors to find that ABT-263, in conjunction with MEK inhibitors, synergistically induced significant inhibition to of tumor growth." (PMID 28025559, 2016).
tumor (continued). "In eight cases, tumor biopsies conducted after treatment were available, and there were 62.5% and 37.5% concordance rates for EGFR and KRAS, respectively." (PMID 27589834, 2016). "Although the majority of both EGFR and KRAS mutant cases were M1b, only 2/22 (9%) EGFR mutant cases had the primary tumor resected versus 4/8 (50%) KRAS mutant patients." (PMID 27448974, 2016). "Specific point mutations in KRAS, especially those at position 12, maintain KRAS in its GTP-bound active form and consequently lead to tumor formation." (PMID 27322423, 2016). "However, the effect of using antiangiogenic drugs beyond progression regarding OS was weaker in the subgroup of women (n = 1,047) with a HR of 0.81 (95%-CI, 0.70–0.94) and not statistically significant for patients bearing a tumor with KRAS mutation (n = 1,260) with a HR of 0.89 (95%-CI, 0.78–1.02)." (PMID 27656206, 2016). "However, the benefit of using antiangiogenic drugs beyond progression regarding OS was weaker in the subgroup of women (n = 1,047) with a HR of 0.81 (95%-CI, 0.70–0.94) and absent in patients bearing a tumor with KRAS mutation (n = 1,260) with a HR of 0.89; 95%-CI, 0.78–1.02." (PMID 27656206, 2016). "In the “dominant” pattern, there were five cancer types, and all of the genes in the “dominant” roles were tumor suppressor genes, except in LUAD, where KRAS, which was an oncogene, dominated in this cancer type." (PMID 26992457, 2016). "Ectopic expression of p16INK4A led to significantly reduced tumor growth induced by activated KRAS4BG12V, emphasizing the tumor-suppressive role of upregulated p16INK4A in KRAS-driven hepatocarcinogenesis." (PMID 26799184, 2016). "Here genetically engineered mouse models (GEMMs) models, and patient-derived xenografts (PDXs) of KRAS, EGFR, and EML-ALK-driven tumours have been instrumental in understanding the key aspects of NSCLC biology." (PMID 27350784, 2016). "More importantly, this study identified miR-16 as a novel link between the KRAS regulatory pathway and CRC and pointed the important role of miR-16 as a tumor suppressor in CRC through the inhibition of KRAS translation." (PMID 27857191, 2016). "Mutant KRAS persistently and directly activates both RAF and PI3K, which has led to the exponential growth of studies aiming to treat KRAS-mutant tumours by coordinately inhibiting both of these pathways." (PMID 27193833, 2016). "More importantly, Aurora kinase targeting reduced anchorage-independent growth of KRAS-transformed lung cells, and inducible inhibition of AURKA expression by RNA interference reduced A549 xenograft tumor growth in vivo." (PMID 26842935, 2016). "One tumor exhibited a high level of FGFR2 amplification with a low level of EGFR and KRAS amplification." (PMID 27014419, 2016). "It will also be useful to understand how KRAS, together with inflammatory and other insults, is capable of downregulating the expression and/or function of PTF1-network components during tumor initiation." (PMID 26151762, 2015). "This system correctly classified all of the tumor and normal samples in the KRAS dataset, in contrast to the 50-DET- and 397-DEE–based systems that erroneously assigned one tumor sample to “normal”." (PMID 26356813, 2015). "This method did allow for the detection of individual mutant KRAS and EGFR sequences in both plasma DNA and platelet RNA, indicating sequestration and potential education capacity of mutant, tumor-derived RNA biomarkers in TEPs." (PMID 26525104, 2015).
tumor (continued). "Such plasticity is thought to arise through interactions between aberrant signaling events, including persistent activation of the APC/β-catenin and KRAS/BRAF/ERK pathways, and the tumor microenvironment." (PMID 25699236, 2015). "Future studies examining the combination of novel inhibitors of KRAS or of epigenetic regulators in combination with energy stress agents and/or targeted therapies may prove an effective strategy for targeting tumours for LKB1/KRASG12C or LKB1/BRG1 co-mutated tumours." (PMID 26196184, 2015). "When certain mutations that may be present in tumours occur, especially in codons 12 and 13 of the KRAS gene, protein activation takes place regardless of the presence of EGFR, which is the target of some drugs for the treatment of this type of cancer, such as panitumumab and cetuximab." (PMID 26557880, 2015). "Mutant KRAS constitutively activates MEK/ERK and PI3K/AKT signaling pathways, both of which are pivotal to the survival and proliferation of tumor cells." (PMID 25946136, 2015). "Although this is the case in some RAS mutant tumor types, including some of the NSCLC tested here, our work indicates that some KRAS mutant cancers retain sensitivity to upstream stimuli emanating from extracellular signaling in particular via the HER pathway." (PMID 25992771, 2015). "For SBTs, bilaterality was found to be significantly more common for KRAS mutant tumours (63.2% versus 26.5%, p = 0.0101, FET), whereas the majority of BRAFV600E mutant tumours (76.2%) were unilateral." (PMID 26506417, 2015). "The AB subpopulation also showed a 50-fold copy number amplification of the KRAS locus on chromosome 12p12.1 and two homozygous deletions of the EFNA5 and COL5A4 tumor suppressors." (PMID 25729435, 2015). "Using a synthetic lethal RNAi screening approach, White and colleagues identified KRAS and LKB1 co-mutant NSCLC tumours to be addicted to coatomer complex I (COPI)-dependent lysosome acidification that supplied macromolecules to the TCA cycle." (PMID 26196184, 2015). "Comparison of the patient tumor and PDX cells revealed a significant enrichment of KRAS mutant tumor areas in the PDX, indicating that this PDX is a good model in which to study KRAS-driven tumors." (PMID 26084335, 2015). "Our results align with previously published data showing a strong link between tumor cell dormancy, various degrees of EMT and KRAS independence." (PMID 26158412, 2015). "In addition, we examined clinical and molecular variables, including tumor location, adjuvant chemotherapy status, microsatellite instability (MSI), CpG island methylator phenotype (CIMP), KRAS mutation and BRAF mutation, to determine whether these characteristics act as confounding factors." (PMID 25875774, 2015). "To determine the status of active EGFR/HER and active KRAS/pan-RAS levels across all treatment groups, we performed both immunoblot analysis and a Raf ‘pull down assay’ on cell lysates extracted from crude tumor tissue." (PMID 25992771, 2015). "In conclusion, the present study identified that miR-27a functions as a tumor suppressor in ESCC, by direct targeting of the KRAS gene." (PMID 25436011, 2015).
tumor (continued). "This literature review aimed to describe the level of mutation status concordance between primary and corresponding metastatic tumours, considering EGFR, KRAS and any other molecular aberrations noted." (PMID 26338018, 2015). "In a multiple logistic regression model with the variables CNV, CIMP, MSI, KRAS, BRAF, stage, tumor localization and gender, the only variable that was retained in the model for recurrence risk was stage." (PMID 25879218, 2015). "In order to improve response to chemotherapy, the PDX was treated with carboplatin/paclitaxel with or without a pan-HER and VEGF inhibitor (BMS-690514) but there was no tumor growth inhibition or improved animal survival, which may be explained by a KRAS mutation." (PMID 25962155, 2015). "For the KRAS analysis, comparable values of mutation load were obtained between early and advanced cancers in both tissue (26.9% vs 34.7%) and plasma samples (1.9% vs 4%), so that the p/t analysis did not reveal significant difference according to tumour stages (8.6% vs 7.3%)." (PMID 25946211, 2015). "We then correlated SLFN11 expression with clinicopathological features of CRC, including primary tumor location, tumor differentiation, preoperative Cancinoembryonic Antigen(CEA) level, TNM staging, KRAS exon 2 status, age and sex." (PMID 26525741, 2015). "When applied to the KRAS dataset, the DET- and DEE-based systems misclassified one tumor sample, but the two DEG-based systems classified all samples correctly." (PMID 26356813, 2015). "The levels of the tumor initiators HER2 and KRAS and metastasis genes VEGF, CXCL-4, CCL5, NEDD9 and RHoC were reduced in MCF-7 cells with UBE2C knockdown and increased with UBE2C overexpression." (PMID 24699941, 2014). "In human tumours, approximately 20% of cases demonstrated low PTEN expression and a gene expression signature that overlaps with murine KRAS PTEN tumours." (PMID 24717934, 2014). "First, genetic heterozygosity within the tumor might result in mutation levels below the analytical sensitivity of dideoxy sequencing (10 - 30%), whereas the detection limit of HRMA was previously reported at 3% and the KRAS StripAssay® detect at least 1% mutated alleles." (PMID 24899223, 2014). "Interestingly, the KRAS mutation could not be detected in the primary CB42 tumor suggesting tumor heterogeneity and clonal selection during propagation." (PMID 25162504, 2014). "In summary, KRAS and BRAF have key roles as driver oncogenes in tumourigenesis in many different types of tumours and depending on the tumour type they can differentially regulate key pathways and genes to provide differential biological effects." (PMID 25361007, 2014). "To determine the generality and clinical relevance of these results, we analyzed other KRAS-positive human CRC cell lines and tumor samples." (PMID 24623306, 2014). "We were also interested in correlating an altered PI3K pathway and a normal PI3K pathway to the NSCLC tumor subtypes ADCA and SCC, gender, smoking status, IRS-1 G972R genotypes as well as to KRAS/BRAF status." (PMID 24500884, 2014). "We therefore sought to determine the role of active KRAS in the RhoGAP-RasGAP interaction, and the effect of this interaction in CRC tumor cells." (PMID 24465899, 2014). "MiR-30c was previously reported to play a suppression role in tumour cell proliferation, metastasis and drug resistance by targeting BCL9, TWF1, vimentin and KRAS." (PMID 24595016, 2014). "Of the four KRAS effector domain mutants, KRASV12/C40 produced the largest increase in tumor size in BrafCA/+ mice, relative to BrafV600E expression alone." (PMID 24489653, 2014). "Here we quantified the benefit of adding the everolimus to irinotecan in KRAS and BRAF mutant CRC tumor models." (PMID 23520486, 2013).
tumor (continued). "This could theoretically lead to false negative results, i.e. there is a KRAS mutation present within a tumour, but the portion sampled for testing does not contain the mutation (or there are insufficient numbers of tumour cells with the mutation) to enable detection." (PMID 23356214, 2013). "Further, this study also identifies the potential of the extracted polyphenols on major tumor progression molecular targets including NFκB, EGFR, kRAS, STAT3, VEGF, AKT, TERT, FGFA, BCl2 and PDGFA." (PMID 23613993, 2013). "In conclusion, expression and functional studies suggest that both miR-433 and miR-127 have tumor suppressive function in GC via targeting MAPK4 and KRAS respectively." (PMID 23880861, 2013). "However, neither low RBM5 expression nor high KRAS expression were proved to be an independent factor associated with higher recurrence rate when corrected with age, gender, tumor size, lymphatic involvement, distant metastasis, cell differentiation, UICC stage and nerve and venous invasion." (PMID 23425895, 2013). "In our cohort, the survival of cetuximab-treated patients with KRAS wild type, AREG-low CRC (median 15 months) was as poor as the survival of patients with KRAS mutant tumours (17–22 months)." (PMID 23374602, 2013). "The low rates of EGFR and KRAS mutations may reflect a higher rate of false-negative results due to the low tumor cell percentage in proportion to non-neoplastic cells in these lymph nodes, although areas of high tumor cellularity were specifically selected for DNA isolation." (PMID 23935846, 2013). "We correlated the KRAS, BRAF and PIK3CA genotypes with clinicopathological features of CRC, including primary tumour location, histological findings, and sites of metastases." (PMID 23617638, 2013). "This study observed that in KRAS wild-type patients, the objective response to anti-EGFR therapy was 0% in BRAF mutant tumours versus 36.3% in BRAF wild-type tumours." (PMID 23356214, 2013). "In conclusion, the utility of the BRAF and KRAS as prognostic biomarkers depends on the MSI status and tumor location." (PMID 24073892, 2013). "Gene expession of the two ligands, which are collocalised on chromosome 4q13.3 and produced by tumour cells in autocrine fashion, was tightly correlated and occurred more often in KRAS and BRAF wild type tumours." (PMID 23374602, 2013). "KRAS is a GTPase in the Ras family and is essential in normal tissue signaling of PI3–kinase but elevated in many cancers where it suppresses tumor suppressor genes." (PMID 22737227, 2012). "The essential finding of this study was that high ex vivo phosphorylation of PI3K-related substrates by the primary tumor, rather than the KRAS/BRAF mutation status, may be a hallmark of poor metastasis-free survival in LARC patients after radical treatment of the pelvic cavity." (PMID 23226389, 2012). "The comparison of median OS of those two groups showed a statistically significant difference which was also accompanied with a better prognosis of patients with wt-KRAS and wt-BRAF tumour." (PMID 22933967, 2011). "Due to the limited amount of metastatic tumor cells in deeper sections, only 22 nuclei were available for the FISH analysis of KRAS and 8 of these displayed amplification." (PMID 22014070, 2011). "We then correlated the KRAS and BRAF genotypes with clinicopathological features of CRC, including primary tumour location, histological findings, and sites of metastases." (PMID 21285991, 2011). "The gene analysis showed amplification of KRAS and ERBB2 oncogenes as possible molecular targets of therapy in tumor cells." (PMID 22014070, 2011). "TTP in the group of patients with wt-KRAS and wt-BRAF tumours and in the group of patients with wt-KRAS and mt-BRAF tumours was 16 months (95% CI: 10.7- 21.2 months) and 12 months (95% CI: 4.0- 15.0 months), respectively." (PMID 22933967, 2011).